GPR55 (G protein-coupled receptor 55)
Diseases named in the same sentence as GPR55 in open-access papers (continued):
Sharing a sentence is not in itself a finding about the gene and the disease.
breast carcinoma (18 papers, 2015 to 2023). "Elevated GPR55 gene expression in breast cancer is associated with reduced disease-free survival, overall survival, and metastasis-free survival, with the highest levels of expression observed in aggressive basal/triple-negative breast tumours." (PMID 32340151, 2020). "Since breast cancer is a very heterogeneous disease, we studied whether GPR55 expression was associated to a specific molecular subtype." (PMID 27340777, 2016). "Previous studies have found that GPR55 is highly expressed in breast cancer, pancreatic cancer, skin cancer and cholangiocarcinoma, and is involved in tumor proliferation and migration." (PMID 37688769, 2023). "GPR55 expression negatively correlates with survival in patients with glioblastoma, breast cancer, and PDAC10,14,15, and genetic ablation of Gpr55 significantly prolonged survival in the KPC transgenic mouse model of PDAC15." (PMID 35256673, 2022). "Expression of GPR34 in hepatocellular carcinoma and that of GPR55 in breast cancer have been reported to be positively correlated with the prognosis." (PMID 35315587, 2022). "In breast cancer, the activation of GPR55 stimulated pro-invasive features by influencing migration of human breast cancer cells." (PMID 34943903, 2021). "In particular, it is known that GPR55 dimerises with CB2R in several tumours such as breast cancer, with implications in cancer malignancy." (PMID 34943903, 2021). "In our study, we show that GPR18, just as for GPR55, contributes to the effects of cannabinoids observed on paclitaxel-resistant breast cancer cell viability." (PMID 31611800, 2019). "CB2R/GPR55 transfected cells and breast cancer cells form GPR55-CB2R heteromers with unique pharmacological and signaling properties." (PMID 31024307, 2019). "For example, GPR55 expression has been detected in breast cancer cell lines and interestingly was much more abundantly expressed in MDA-MB-231 cells compared with the less metastatic MCF-7." (PMID 31611800, 2019). "Activation of GPR55 by its proposed endogenous ligand lysophosphatidylinositol confers pro-invasive features on breast cancer cells both in vitro and in vivo." (PMID 27340777, 2016). "Recently, it has been demonstrated that miR-675 have several targets in different cancers, such as c-Cbl and Cbl-b in breast cancer, GPR55 in lung carcinoma, Rb in colorectal cancer, CALN1 in gastric cancer, Cadherin 11 in melasma." (PMID 27120794, 2016). "Another study showed a highly migratory effect of LPI (1 μm) on the metastatic MDA-MB231 breast cancer cell line, which expresses GPR55." (PMID 26730399, 2015). "To understand the role of GPR55 in the advanced stages of breast cancer progression, we first investigated whether there was an association between GPR55 levels and patient prognosis." (PMID 27340777, 2016). "Together, these data show that GPR55 promotes breast cancer metastasis, and supports the notion that this orphan receptor may constitute a new therapeutic target and potential biomarker in the highly aggressive triple-negative subtype." (PMID 27340777, 2016). "Therefore, we measured the expression of GPR55 in the breast cancer cell lines by Western blot." (PMID 33081264, 2020). "Our results show that activation of GPR55 promotes metastasis in breast cancer, thus supporting that this receptor may be exploited as a new target in oncology, specifically in the metastatic disease associated to the highly aggressive triple-negative breast cancer." (PMID 27340777, 2016). "Pancancer analysis revealed that overexpression of GPR55 is a protective factor for much better overall survival and better disease-free survival in HCC, breast cancer, and Uterine Corpus Endometrioid Carcinoma." (PMID 37688769, 2023). "Our results suggest that some cannabinoids acting through the GPR55 and/or GPR18 receptors can be helpful in inducing apoptosis in breast cancer cell lines that are unresponsive to paclitaxel." (PMID 31611800, 2019).
breast carcinoma (continued). "In breast cancer, LPI treatment of MDA-MB-231 cells enhances cell chemotaxis, which was prevented by transfection with GPR55 small interfering RNA." (PMID 31611800, 2019). "Furthermore, GPR55 has been reported to regulate CB2-mediated chemotaxis of human neutrophils and to modulate migration and polarisation of human breast cancer cells." (PMID 33902596, 2021). "In prostate (PC-3, DU145 and LNCaP) and ovarian (OVCAR3 and A2780) cancer cell lines, an autocrine loop that involves GPR55, LPI and the ABC transporter ABCC1 has been demonstrated, whilst GPR55 expression enhances the invasion and migration of human breast cancer cells." (PMID 34324032, 2021). "Importantly, previous studies have shown that CBD (5 mg/kg) inhibits the growth of MDA-MB-231 breast cancer cells in vivo using xenograft mouse models, once again highlighting a potential role for CBD in the treatment of GPR55 overexpression and aggressive cancer types." (PMID 32340151, 2020).
colon cancer (14 papers, 2016 to 2025). "In the experiment using the GPR55-/- colitis-associated colon cancer mice model, the levels of COX-2, STAT3, thromboxane A2, PGF2α and myeloid cell-recruiting chemokine monocyte chemoattractant protein-1 were lower than in the wild-type mice." (PMID 34503163, 2021). "GPR55 has also been indirectly associated to both pro-angiogenic responses and to pro-migratory phenotypes in breast and colon cancer cells." (PMID 27340777, 2016). "In this study we reinvestigated the relationship between colon cancer (CC) and GPR55, focusing on analysis of patients’ lymph nodes obtained from curative surgery." (PMID 35562947, 2022). "Knocking down the GPR55 receptors in mice models increased the levels of CD4+ and CD8+ cells in the tumor beds, which emphasizes the role of GPR55 in inflammation-induced colon cancers." (PMID 34503163, 2021). "In this study, the prognostic value of GPR55 in colon cancer (CC) was investigated." (PMID 35562947, 2022). "Through its ultramicronized form, Palmidrol exhibits inhibitory effects on tumors by suppressing colon cancer cell proliferation via the activation of peroxisome proliferator-activated receptor α (PPAR-α) and G protein-coupled receptor 55 (GPR55)." (PMID 40028184, 2025). "In HCT116 colon cancer cells, RGS2 was shown to interact with GPR55, effectively suppressing GPR55-mediated oncogenic signaling." (PMID 40754247, 2025). "G-protein coupled receptor 55 (GPR55), a lysophospholipid receptor, has been shown to play an important role in the migration and metastasis in colon cancer cells." (PMID 33916164, 2021). "The GPR55 antagonist CID 16020046 (1, 2.5, 5 μM), CBD (1, 2.5 μM), a putative GPR55 antagonist and GPR55 small interfering RNA (siRNA) were used to block GPR55 activity of HCT116 colon cancer cells." (PMID 31775230, 2019). "Interestingly, an interaction between GPR55 and S1P5 receptor has already been demonstrated in a colon cancer cell line." (PMID 36232401, 2022). "GPR55, which is known to be a specific receptor of LPI and partially of LPG50, 51, 52, has been reported to be involved in the development of metastasis in colon cancer, and its down‐regulation was shown to reduce tumour growth in an animal model." (PMID 36125914, 2022). "GPR55 can activate a cascade of reactions involving calcium mobilization, ERK1/2 phosphorylation, adhesion, and migration of colon cancer cells that may lead to liver metastasis." (PMID 34503163, 2021).
colitis (13 papers, 2016 to 2025). Inflammation of the colon. "Data from dextran sulfate sodium (DSS)-induced colitis model in mice indicate that the receptor contributes to intestinal inflammation, since GPR55-deficient animals develop significantly less severe colitis than wild types." (PMID 34948125, 2021). "Corroborating this, when treated with an antagonist of GPR55, CID16020046 or GPR55−/− knockout (GPR55ko) mice exhibited a decrease in pro-inflammatory cytokines in a colitis mouse model." (PMID 38334672, 2024). "It has been reported that PEA improves murine experimental colitis and that this effect is, at least partially, mediated by GPR55 activation." (PMID 31396087, 2019). "Corroborating with this, an antagonist of GPR55, CID16020046, and GPR55−/− knockout mice decreased the pro-inflammatory cytokines in colitis mice models comparable to human inflammatory bowel disease (IBD)." (PMID 30453998, 2018). "CID16020046, a specific GPR55 antagonist, reduced colon inflammation in a murine colitis model." (PMID 40429822, 2025). "This may indicate that either PACAP-derived peptides ameliorate colitis in a GPR55-independent manner or show a signaling bias toward GPR55." (PMID 34948125, 2021). "Corroborating with this, an antagonist of GPR55, CID16020046, as well as GPR55−/− knockout mice decreased pro-inflammatory cytokines in mice models of colitis comparable to human inflammatory bowel disease (IBD)." (PMID 33801492, 2021). "In contrast, O-1602 (a GPR55 agonist) showed a protective effect against experimentally induced colitis, reducing inflammation and inhibiting neutrophil migration even in CB1/CB2 and GPR55 knockout mice." (PMID 35003109, 2021). "In experimental colitis model, GPR55 knockout mice showed less severe symptoms, and CID16020046, a potent GPR55 antagonist, reduced colon inflammation." (PMID 33494185, 2021). "GPR55 expression was increased in the GI tract during sepsis and GPR55 knockout mice showed least severe intestinal inflammation in comparison to CB1R or CB2R knockout mice in experimental colitis." (PMID 27597829, 2016).
glioblastoma (13 papers, 2015 to 2026). The most malignant astrocytic tumor (WHO grade IV). "GPR55 overexpression is associated with poor prognosis in glioblastoma patients, correlating with lower overall survival." (PMID 40565152, 2025). "Cannabichromene (CBC), cannabigerol (CBG), cannabidiol (CBD), and Piper nigrum derivates exhibited strong binding affinities relative to glioblastoma-associated targets GPR55 and PINK1." (PMID 40565152, 2025). "Higher histological grade human glioblastomas have been reported to be associated with increased GPR55 expression." (PMID 25926795, 2015). "Higher GPR55 expression is associated with more aggressive phenotypes (higher histological grades and higher proliferative rates) in human breast tumors, pancreatic tumors and glioblastomas." (PMID 25889562, 2015). "Analyses of glioblastoma patients with high versus low GPR55 expression further support its prognostic relevance, as elevated GPR55 mRNA levels within the tumor are associated with reduced survival." (PMID 40565152, 2025). "In contrast, GPR55 was expressed in both control and tumor tissues, with significantly higher intensity in glioblastoma samples, indicating a potential role in tumor progression." (PMID 40565152, 2025). "Previously, we reported a reduction in Ki67-immunoreactive nuclei of human glioblastoma cells after GPR55 activation in general by THC and in particular by LPI." (PMID 37998380, 2023). "The present study was designed to shed light on part of the possible intracellular mechanisms downstream of GPR55 that decrease the number of Ki67 immunoreactive nuclei of human glioblastoma when these become activated by THC or LPI." (PMID 37998380, 2023). "We recently discovered that THC affected the number of Ki67+ nuclei from patient-derived cells of human glioblastomas by GPR55." (PMID 37998380, 2023). "Earlier in vitro studies indicated that both (R,R′)-MNF and (R,S′)-MNF reduce proliferation of 1321N1 astrocytoma, U118MG glioblastoma, and HepG2 hepatocellular carcinoma cells suggesting that both compounds target GPR55 and β2-AR." (PMID 35256673, 2022). "Silencing GPR55 in a xenograft model of glioblastoma slowed tumor growth and reduced the number of proliferation cells within the tumors." (PMID 25926795, 2015). "Additionally, immunohistochemical (IHC) analyses of PINK1 and GPR55 were performed on glioblastoma samples from Colombian patients, providing insights into their expression patterns in tumor tissues." (PMID 40565152, 2025). "Furthermore, another study demonstrated that downregulation of GPR55 in a xenograft mice model of glioblastoma reduces tumour growth and that GPR55 knockout mice are more resistant to skin carcinogenesis." (PMID 26784247, 2016). "However, the analysis of additional transcription factors, which are influenced by IP3-driven Ca2+ release and/or calcineurin, should be elucidated in future investigations to shed light on the precise mechanism of the GPR55-mediated reduction of Ki67+ nuclei in glioblastoma cells." (PMID 37998380, 2023). "Emerging evidence highlights molecular targets like GPR55 and PINK1 as key players in glioblastoma progression." (PMID 40565152, 2025). "As the present study showed similarities and differences in GPR55-associated signaling compared to the literature, we may anticipate a better understanding of the complex pathways by which THC and GPR55 affect tumor cell biology in the context of glioblastomas." (PMID 37998380, 2023). "This figure compares the expression of PINK1 and GPR55 in glioblastoma tumor tissues versus a non-tumoral human cortex, highlighting their potential associations with glioblastoma characteristics." (PMID 40565152, 2025).
glioblastoma (continued). "However, previous reports indicate considerable GPR55 expression in SH-SY5Y, T98G, and U87MG cells and other models, suggesting its potential role in glioblastoma pathophysiology and therapeutic responses." (PMID 40565152, 2025). "Moreover, the treatment of human patient-derived glioblastoma cells with ∆9-THC has been shown to reduce the number of Ki67-labelled cells, through the orphan cannabinoid receptor GPR55." (PMID 35242036, 2022).
pancreatic cancer (13 papers, 2019 to 2025). "As to pancreatic cancer, genetic ablation of GPR55 in a PDAC model clearly improved disease outcome." (PMID 39885986, 2024). "Its influence on the metabolism of pancreatic cancer cells has been also demonstrated through the actions of (R, R’)-4’-methoxy-1-naphthylfenoterol, which, by modulating GPR55 signaling, altered L-lactose metabolism in PANC-1 cells and mice xenografts." (PMID 39885986, 2024). "Knowing that GPR55 is highly expressed in pancreatic cancer, we generated a KPCY cell line (KPCY55) that stably overexpressed GPR55." (PMID 39885986, 2024). "As to pancreatic cancer, inhibition of GPR55 revealed antitumor effects in a human pancreatic cancer cell line." (PMID 39885986, 2024). "In KPCY tumors of GPR55 KO mice, we also detected a decrease of neutrophils vs. WT tumors, which fits with the mostly pro-tumorigenic role of neutrophils in pancreatic cancer." (PMID 39885986, 2024). "To this end, we used KPCY tumor cells (from mouse PDAC), and - since GPR55 is highly expressed in human pancreatic cancer cells and higher stage pancreatic intraepithelial neoplasia - KPCY tumor cells that overexpressed GPR55 (termed KPCY55)." (PMID 39885986, 2024). "CAR-T cells isolated 30 days after adoptive transfer into mice bearing HPAC-derived pancreatic tumor displayed a decrease in GPR55 in comparison to pre-infused cells." (PMID 34948125, 2021). "Similarly, in pancreatic cancer, the GPR55 inhibitor (R,R’)−4’-methoxy-1-naphthylfenoterol (MNF) suppresses tumor proliferation and enhances sensitivity to chemotherapeutics such as doxorubicin and gemcitabine." (PMID 40434517, 2025). "The role of other cannabinoid receptors including GPR55 has been speculated to be involved in regulating many cancer types including pancreatic cancer." (PMID 34259916, 2021). "Regarding the increase in tumor burden in GPR55 WT mice, it should be noted that cancer patients can paradoxically respond with increased tumor progression to immune checkpoint inhibitor therapy (hyperprogressive disease), something that has been now also reported for advanced pancreatic cancer." (PMID 39885986, 2024). "Since changes in the immune TME of GPR55 KO mice were more pronounced in KPCY55 than KPCY tumors, and high expression of GPR55 was reported in human pancreatic cancer, we used KPCY55 tumors for RNA-seq evaluation and for further in vivo experiments." (PMID 39885986, 2024). "The G protein-coupled receptor 55 (GPR55) is part of an expanded endocannabinoid system (ECS), and plays a pro-tumorigenic role in different cancer models, including pancreatic cancer." (PMID 39885986, 2024). "An experimental investigation revealed that GPR55 promotes the proliferation and growth of pancreatic cancer tumors through MAPK signaling, and inhibition of GPR55 increases the therapeutic effects of gemcitabine." (PMID 37688769, 2023). "Due to their ability to agonise GPR55 activity, LPI, specifically arachidonoyl-LPI, plays a role in pancreatic cancer progression." (PMID 35204820, 2022). "We have shown previously that pancreatic cancer cells also efflux LPI which, in turn, activates GPR55 in a similar autocrine loop." (PMID 32718079, 2020). "The G protein-coupled receptor 55 (GPR55) activates both PI3K/AKT and the MEK/ERK1/2 axis, and promotes the nuclear translocation of HIF-1α and β-catenin, two inducers of Pgp and BCRP in pancreatic cancer cells." (PMID 31117237, 2019). "In an in vivo pancreatic cancer study on KPCG mice, which do not express GPR55 on PDAC cells, we confirmed that the absence of the GPR55 receptor significantly increased survival compared to the KPC control." (PMID 35204820, 2022).